NMNAT3 (nicotinamide nucleotide adenylyltransferase 3)
Description:
Catalyzes the formation of NAD(+) from nicotinamide mononucleotide (NMN) and ATP. Can also use the deamidated form; nicotinic acid mononucleotide (NaMN) as substrate with the same efficiency. Can use triazofurin monophosphate (TrMP) as substrate. Can also use GTP and ITP as nucleotide donors. Also catalyzes the reverse reaction, i.e. the pyrophosphorolytic cleavage of NAD(+). For the pyrophosphorolytic activity, can use NAD(+), NADH, NaAD, nicotinic acid adenine dinucleotide phosphate (NHD), nicotinamide guanine dinucleotide (NGD) as substrates. Fails to cleave phosphorylated dinucleotides NADP(+), NADPH and NaADP(+). Protects against axonal degeneration following injury. May be involved in the maintenance of axonal integrity (By similarity). Also functions as a stress-response chaperone protein that prevents toxic aggregation of proteins; this function may be independent of its NAD(+) synthesis activity.
Synonyms: PNAT-3; FKSG76; PNAT3
Tractability: Small molecule: a structure with a bound ligand is known; it has a high-quality binding pocket.
Gene: Protein-coding gene on chromosome 3 (139,558,709 to 139,678,017, reverse strand). Ensembl gene ENSG00000163864.
Subcellular location: Mitochondrion
Subcellular location (Human Protein Atlas): Mitochondria
Pathways (Reactome):
Metabolism: Nicotinate metabolism
Gene Ontology:
Molecular function: nicotinamide-nucleotide adenylyltransferase activity; nicotinate-nucleotide adenylyltransferase activity; catalytic activity; nucleotidyltransferase activity
Biological process: NAD+ biosynthetic process via the salvage pathway; nucleotide biosynthetic process; NAD+ biosynthetic process; response to tumor necrosis factor
Cellular component: mitochondrion; mitochondrial matrix; axon; neuronal cell body
Genetic constraint (gnomAD): Loss-of-function variants: 11 observed, 12.73 expected, observed/expected ratio (o/e) 0.86, 90% interval 0.54 to 1.43. The upper end of that interval is the gene's LOEUF score, 1.43, which puts it in group 5 of 6, group 1 being the genes least tolerant of losing a copy. Missense variants: 310 observed, 333.02 expected, observed/expected ratio (o/e) 0.93, 90% interval 0.85 to 1.02. Synonymous variants: 106 observed, 124.2 expected, observed/expected ratio (o/e) 0.85, 90% interval 0.73 to 1.
Homologues: Orthologues: chimpanzee NMNAT3 (99% identical), macaque RBP1 (95% identical), pig NMNAT3 (81% identical), mouse Nmnat3 (80% identical), dog NMNAT3 (80% identical), rat Nmnat3 (80% identical), guinea pig NMNAT3 (79% identical), zebrafish nmnat3 (54% identical). Paralogues in human: NMNAT1 (50% identical), NMNAT2 (43% identical).
Diseases named in the same sentence as NMNAT3 in open-access papers:
NMNAT3 is named in the same sentence as 27 diseases in open-access papers, as found by Europe PMC text mining. Sharing a sentence is not in itself a finding about the gene and the disease. The quoted sentences say what the papers report.
glaucoma (3 papers, 2013 to 2021). Increased pressure in the eyeball due to obstruction of the outflow of aqueous humor. "Quantitative analysis confirmed that overexpression of Nmnat3 exerted a significant protective effect against axonal loss induced by IOP elevation (P<0.05 versus experimental glaucoma)." (PMID 24136224, 2013). "This protective effect was significantly inhibited by 3-MA, an autophagy inhibitor (P<0.05 versus experimental glaucoma+Nmnat3 transfection)." (PMID 24136224, 2013). "In the glaucoma+Nmnat3 transfection and glaucoma+rapamycin groups, myelin and microtubule structures were well preserved, and no apparent degenerative changes were observed." (PMID 24136224, 2013). "Autophagic vacuoles were observed in the glaucoma, glaucoma+Nmnat3 transfection, and glaucoma+rapamycin groups." (PMID 24136224, 2013). "NMNAT3 upregulation in two different mouse models of glaucoma exerted significant protection of axons that could be reversed with treatment by 3-methyladenine, a PI3K inhibitor that reduces autophagy." (PMID 28424571, 2017). "Electron microscopy showed the existence of autophagic vacuoles in optic nerve axons in the glaucoma, glaucoma+Nmnat3 transfection, and glaucoma+rapamycin groups, although preserved myelin and microtubule structures were noted in the glaucoma+Nmnat3 transfection and glaucoma+rapamycin groups." (PMID 24136224, 2013). "In addition to raised levels being seen with metformin treatment, NAD+ may be naturally regenerated by nicotinamide mononucleotide adenylyltransferase-3 (NMNAT3) as a protective mechanism against the mitochondrial dysfunction that precedes axon degeneration in glaucoma." (PMID 34440899, 2021). "Strategies used to protect against axon degeneration in glaucoma in particular consist of providing glucose, upregulating NMNAT1 and NMNAT3, providing ketone bodies, and inhibiting histone deacetylases (HDACs)." (PMID 28424571, 2017). "Nmnat3 transfection decreased p62 and increased LC3-II in the optic nerve both with and without experimental glaucoma." (PMID 24136224, 2013). "Nmnat3 transfection and rapamycin resulted in further elevation of LC3-II protein levels, but 3-MA did not, in the optic nerve in the glaucoma group." (PMID 24136224, 2013).
glioma (3 papers, 2021 to 2023). A benign or malignant brain and spinal cord tumor that arises from glial cells (astrocytes, oligodendrocytes, ependymal cells). "In our study NAMPT, NMNAT1 and NMNAT3 were found significantly upregulated in glioma samples compared to the controls." (PMID 36809279, 2023). "The NMRGS score of every glioma patient was obtained as follows: NMRGS score = (-0.28992*CD38 expression) + (0.38315*NADK expression) + (-0.04654*NAPRT expression) + (0.2211*NMNAT3 expression) + (-0.24486*PARP6 expression) + (0.29991*PARP9 expression)." (PMID 36845744, 2023). "Oncometabolic rate assessment analysis showed significant increased ATP level (p<0.0001), NAD+ level [(NMNAT1 (p<0.0001), NMNAT3 (p<0.0001) and NAMPT (p<0.04)] and glutathione level (p<0.0001) in glioma patients compared to controls." (PMID 36809279, 2023). "Contrary to expectations, except for NMNAT3, the expression of other hub genes was not consistently overexpressed or underexpressed in these glioma cell lines compared to NHA." (PMID 36845744, 2023).
Insulin resistance (2 papers, 2018 to 2019). Increased resistance towards insulin, that is, diminished effectiveness of insulin in reducing blood glucose levels. "Nmnat3 Tg mice exhibit metabolically beneficial effects against aging- and diet-associated insulin resistance with increased levels of NAD, NGD, and NHD17." (PMID 31511627, 2019). "We also demonstrated that Nmnat3‐overexpressing (Nmnat3 Tg) mice were protected against diet‐induced and aging‐associated insulin resistance." (PMID 29901258, 2018). "Therefore, reduced ROS levels would likely be protective against diet‐induced and aging‐associated insulin resistance in Nmnat3 Tg mice." (PMID 29901258, 2018). "Therefore, increased ratios of complex II to complex I in Nmnat3 Tg mice probably reduce ROS generation and ameliorate age‐associated insulin resistance." (PMID 29901258, 2018). "In this study, we employed Nmnat3‐overexpressing (Nmnat3 Tg) mice and assessed the impacts of Nmnat3 gain of function on NAD metabolism and aging‐associated phenotypes, including insulin resistance." (PMID 29901258, 2018).
Splenomegaly (2 papers, 2016 to 2020). Abnormal increased size of the spleen. "On the other hand, NMNAT3 deficient mice (NMNAT3 KO) are viable with splenomegaly and hemolytic anemia." (PMID 33107823, 2020). "The aged Nmnat3-KO mice exhibited splenomegaly in young Nmnat3-KO mice." (PMID 26756334, 2016). "Previously, we have demonstrated that Nmnat3 was strongly expressed in mature erythrocytes, which lacked mitochondria, and Nmnat3-deficient mice exhibited splenomegaly and hemolytic anemia." (PMID 26756334, 2016). "Previously, we have reported that murine Nmnat3 protein was strongly expressed in the cytoplasm of mature erythrocytes, in which mitochondria were absent, and Nmnat3-deficient mice (Nmnat3-KO mice) exhibited splenomegaly and hemolytic anemia due to reduced NAD levels in mature erythrocytes." (PMID 26756334, 2016). "Consistent with the previous report, NMNAT3 KO mice showed splenomegaly (data not shown), however, there were no defects in ERG." (PMID 33107823, 2020).
age (1 paper, 2018). A temporal measurement of the time period elapsed since an identifiable point in the life cycle of an organism. "Taken together, the present data warrant further consideration of Nmnat3 as a promising target for the treatment of various age‐associated metabolic diseases." (PMID 29901258, 2018).
Alpha-synucleinopathy (1 paper, 2022). "Our results establish, for the first time, NMNAT3 alterations in Parkinson’s disease and demonstrate in human cells that this phenotype together with neurite pathology is causally related to α-synucleinopathy." (PMID 35397003, 2022).
Alzheimer disease (1 paper, 2022). A progressive, neurodegenerative disease characterized by loss of function and death of nerve cells in several areas of the brain leading to loss of cognitive function such as memory and language. "In contrast, NMNAT3 protein levels in PD subjects were independent of both Tau score and Alzheimer’s disease (AD) pathology." (PMID 35397003, 2022).
dementia (1 paper, 2022). Loss of intellectual abilities interfering with an individual's social and occupational functions. "NMNAT3 protein levels were significantly higher in PD subjects with dementia than those without (0.5 ± 0.11 versus 0.19 ± 0.04, P = 0.02, n = 12 and 6, respectively)." (PMID 35397003, 2022).
endometriosis (1 paper, 2021). The growth of functional endometrial tissue in anatomic sites outside the uterine body. "Our study suggested that ProEGCG binds to NMNAT1 and NMNAT3 molecules in human endometrial stromal cells and validated in endometriosis mouse model." (PMID 34721014, 2021). "Endometriosis mice model was successfully developed to study the therapeutics effects of EGCG and ProEGCG, and the interaction involved in NMNAT1 and NMNAT3 PPI network, as enriched by Strings." (PMID 34721014, 2021). "NMNAT1 and NMNAT3 had expressions in the endometrial stromal cells, were genes that undergo transcription in endometriosis and had the most negative Gibbs free energy, denoting the most substantial binding with ProEGCG (NMNAT1: −8.7 kJ/mol; NMNAT3: −10 kJ/mol)." (PMID 34721014, 2021).
Glucose intolerance (1 paper, 2018). Glucose intolerance (GI) can be defined as dysglycemia that comprises both prediabetes and diabetes. "Taken together, these findings indicate that increased Nmnat3 expression alleviates aging‐associated glucose intolerance by increasing insulin sensitivity." (PMID 29901258, 2018).
hypercoagulability (1 paper, 2025). "In conclusion, JHP ameliorates early NONFH by regulating lipid metabolism, improving hypercoagulability, and restoring bone homeostasis through the NMNAT1/NMNAT3/NAMPT/STK11/HMGCR/ACAT1 axis." (PMID 40988117, 2025).
Infertility (1 paper, 2024). "We found that supplementing animals with the NAD+ precursor nicotinamide mononucleotide (NMN), or genetic overexpression of the NAD+ biosynthetic enzymes NMNAT1 and NMNAT3, could protect against infertility caused by the drugs doxorubicin and cisplatin." (PMID 39169162, 2024). "As a model for chemotherapy induced infertility we used two chemotherapy agents (doxorubicin and cisplatin), testing three interventions (NMN treatment, NMNAT1-Tg and NMNAT3-Tg overexpression) and using three outcomes for fertility (COC yield, breeding, ovarian histology)." (PMID 39169162, 2024).
ischemia (1 paper, 2025). A hypoperfusion of the BLOOD through an organ or tissue caused by a PATHOLOGIC CONSTRICTION or obstruction of its BLOOD VESSELS, or an absence of BLOOD CIRCULATION. "Our results for NMNAT3 (mitochondrial isoform) are different from other studies that used NMDA as an excitotoxic agent and also from models of ischemia." (PMID 40277908, 2025).
liver fibrosis (1 paper, 2024). "After grouping the dataset based on liver fibrosis stages in the Gene Expression Omnibus, we compared expression values of NMNAT3 and NAMPT." (PMID 39143151, 2024). "The expression of NAD+ biosynthesis rate-limiting enzymes, nicotinamide phosphoribosyltransferase (NAMPT) and nicotinamide mononucleotide adenylyltransferase 3 (NMNAT3), were upregulated significantly in the liver tissue of patients with higher liver fibrosis stages (p < 0.0001)." (PMID 39143151, 2024).
nicotine addiction (1 paper, 2023). "T2DM adults metabolize nicotine more rapidly, NMNAT3 genes overexpression in our data may provide a possible explanation for the nicotine addiction of T2DM, as highlighted before." (PMID 36528847, 2023).
Obesity (1 paper, 2018). Accumulation of substantial excess body fat. "Thus, we investigated whether Nmnat3 overexpression can compensate for NAD deficiencies in skeletal muscle due to diet‐induced obesity." (PMID 29901258, 2018).
pancreatic tumor (1 paper, 2023). "However, the role of COQ4, MCRIP2, MRPL50, MRPL14, RFK, and NMNAT3 in pancreatic tumor has not been reported." (PMID 37223030, 2023).
Parkinson disease (1 paper, 2022). A progressive degenerative disorder of the central nervous system characterized by loss of dopamine producing neurons in the substantia nigra and the presence of Lewy bodies in the substantia nigra and locus coeruleus. "Here we report significantly decreased levels of NMNAT3 protein in the caudate nucleus of patients who have died with Parkinson’s disease, which inversely correlated with the amount of monomeric α-synuclein." (PMID 35397003, 2022).
psoriasis (1 paper, 2021). An autoimmune condition characterized by red, well-delineated plaques with silvery scales that are usually on the extensor surfaces and scalp. "The mRNA levels NAMPT were upregulated, while those of NMNAT3 were down-regulated in psoriasis lesional skin." (PMID 34748530, 2021).
tumor (4 papers, 2015 to 2024). "Other genes were modulated in a different way in all three SCCs (NMNAT1, NMNAT2, NADSYN1, SIRT3, and CD38) or in two tumor types (NNMT, NMNAT3, ENPP2, PNP, and SIRT1)." (PMID 38254798, 2024). "Compared with ubiquitously expressed NMNAT1 and NMNAT3, NMNAT2 mRNA was reported to be mainly expressed in high energy consumption tissues such as brain, heart, skeletal muscle, and some tumor tissues." (PMID 27218101, 2016).
metabolic disease (2 papers, 2018 to 2021). A congenital disorder (due to inherited enzyme abnormality) or acquired (due to failure of a metabolically important organ) disorder resulting from an abnormal metabolic process. "Moreover, overexpression of Nmnat3 improves metabolic health and is an attractive therapeutic target for aging‐related metabolic disorders." (PMID 33528041, 2021).
NMNAT3 also shares sentences with these, for which no sentence is quoted: bladder cancer (1 paper); haemolytic anaemia (1); heart failure (1); Immunodeficiency (1); neuroblastoma (1); neurologic diseases (1).